RN7SL863P (RNA, 7SL, cytoplasmic 863, pseudogene)
Gene: Miscellaneous RNA gene on chromosome 3 (62,796,124 to 62,796,419, reverse strand). Ensembl gene ENSG00000244632.
Homologues: Orthologues: chimpanzee Metazoa_SRP (99% identical), macaque Metazoa_SRP (89% identical), dog Metazoa_SRP (55% identical). Paralogues in human: RN7SL3 (80% identical), RN7SL1 (79% identical), RN7SL2 (79% identical), RN7SL45P (78% identical), RN7SL464P (77% identical), RN7SL709P (77% identical), RN7SL856P (77% identical), RN7SL126P (77% identical), RN7SL230P (77% identical), RN7SL448P (77% identical), RN7SL597P (77% identical), RN7SL630P (77% identical), and 706 more.